TRMT44 (tRNA methyltransferase 44 homolog)
Description:
Probable adenosyl-L-methionine (AdoMet)-dependent tRNA (uracil-O(2)-)-methyltransferase.
Synonyms: C4orf23; METTL19; FLJ35725; TRM44
Tractability: PROTAC: ubiquitination databases record sites on it.
Gene: Protein-coding gene on chromosome 4 (8,436,140 to 8,493,531, forward strand). Ensembl gene ENSG00000155275.
Subcellular location: Cytoplasm
Subcellular location (Human Protein Atlas): Cytosol; Nuclear bodies
Pathways (Reactome):
Metabolism of RNA: tRNA modification in the nucleus and cytosol
Gene Ontology:
Molecular function: tRNA (uridine) methyltransferase activity; metal ion binding; methyltransferase activity; tRNA(Ser) (uridine(44)-2'-O-)-methyltransferase activity
Biological process: tRNA methylation
Cellular component: cytoplasm
Genetic constraint (gnomAD): Loss-of-function variants: 64 observed, 66.15 expected, observed/expected ratio (o/e) 0.97, 90% interval 0.79 to 1.19. The upper end of that interval is the gene's LOEUF score, 1.19, which puts it in group 5 of 6, group 1 being the genes least tolerant of losing a copy. Missense variants: 1,041 observed, 937.57 expected, observed/expected ratio (o/e) 1.11, 90% interval 1.05 to 1.17. Synonymous variants: 376 observed, 377.94 expected, observed/expected ratio (o/e) 0.99, 90% interval 0.91 to 1.08.
Homologues: Orthologues: chimpanzee TRMT44 (99% identical), macaque TRMT44 (93% identical), dog TRMT44 (70% identical), guinea pig TRMT44 (70% identical), pig TRMT44 (66% identical), mouse Trmt44 (66% identical), rat Trmt44 (66% identical), tropical clawed frog trmt44 (48% identical), zebrafish trmt44 (43% identical), Drosophila melanogaster CG9386 (25% identical), Caenorhabditis elegans C23G10.7 (22% identical).
Diseases named in the same sentence as TRMT44 in open-access papers:
TRMT44 is named in the same sentence as 4 diseases in open-access papers, as found by Europe PMC text mining. Sharing a sentence is not in itself a finding about the gene and the disease. The quoted sentences say what the papers report.
partial epilepsy (2 papers, 2020 to 2023). "A previous report indicated that TRMT44 plays a causal factor of partial epilepsy with pericentral spikes (PEPS)." (PMID 32401299, 2020). "The TRMT44 gene is associated with partial epilepsy with pericentric spikes, and the NPHP1 is associated with Joubert's syndrome, which can alter the nuclei of the medulla oblongata in addition to the base of the pons, causing various neuropathological changes." (PMID 37884635, 2023).
TRMT44 also shares sentences with these, for which no sentence is quoted: cancer (1 paper); colorectal cancer (1); Joubert syndrome (1).